SNHG20 (small nucleolar RNA host gene 20)
Diseases named in the same sentence as SNHG20 in open-access papers (continued):
Sharing a sentence is not in itself a finding about the gene and the disease.
cancer (25 papers, 2016 to 2025). A tumor composed of atypical neoplastic, often pleomorphic cells that invade other tissues. "SNHG20, on the other hand, has only one variant which is upregulated in cancer and possesses a G4-forming site." (PMID 37628839, 2023). "Therefore, it can be speculated that SNHG20 coexpressed with has-miR-331-3p was associated with promoting cancer development by necroptosis." (PMID 35371342, 2022). "Small nucleolar RNA host gene 20 (SNHG20) has been recognized as a critical lncRNA in multiple human cancers." (PMID 38886753, 2024). "Upregulated SNHG20 expression is capable of serving as an innovative predictive factor of inferior clinical outcomes in cancer patients." (PMID 34650970, 2021). "There is growing evidence indicating that lncRNA SNHG20 is closely involved in the development of many cancer processes." (PMID 34282711, 2021). "We found that over-expression of SNHG12 and SNHG20 in LIHC had significant alteration across cancer stages, representing their roles in cancer progression and invasion." (PMID 35140741, 2021). "Four articles consisting of 350 cases exhibited the prognostic role of SNHG20 on cancer progression or recurrence, with a pooled HR of 2.37 (95% CI 1.60–3.51, P = 0.000)." (PMID 32675944, 2020). "There is increasing evidence that long non‐coding RNA (lncRNA) small nucleolar RNA host gene 20 (SNHG20) plays an important role in cancer." (PMID 33089952, 2020). "Herein, we carry out a systematic meta-analysis to further determine the prognostic and clinical significance of SNHG20 expression in various human cancers." (PMID 32675944, 2020). "SNHG20 promotes gastric cancer by stimulating cancer cell proliferation, cell cycle progression, invasion, and migration." (PMID 32318335, 2020). "Of note, enforced SNHG20 expression predicted a poor performance for DFS/RFS/PFS in the involved cancer types compared with low SNHG20 expression." (PMID 32675944, 2020). "Previous published studies have elucidated that SNHG20 was a cancer-related lncRNA and had an indispensable role in oncogenic activity." (PMID 32675944, 2020). "Taken together, the anomalous modulation of SNHG20 across different kinds of cancers suggests that SNHG20 is qualified as a candidate biomarker for both forecasting poor prognosis and providing therapeutic targets in cancer patients." (PMID 32675944, 2020). "The results of the research uncovered that enhanced SNHG20 expression was predominantly interrelated with short OS in cancer patients." (PMID 32675944, 2020). "A total of fifteen studies comprising 1187 patients focused on assessing the effect of SNHG20 overexpression on OS in various kinds of cancer." (PMID 32675944, 2020). "The long noncoding RNA small nucleolar RNA host gene 20 (SNHG20) has been demonstrated to play a crucial role in cancer progression." (PMID 30846486, 2019). "Newly confirmed and functional lncRNA, SNHG20 influences not only cancer cells proliferation, metastasis and as prognostic factors, but also EMT and mitochondrial apoptosis." (PMID 30846486, 2019). "Enhanced expression of lncRNA small nucleolar RNAs (Sox2ot), small nucleolar RNA host gene 20 or prostate cancer non-coding RNA 1 promotes cell migration and invasion in CRC." (PMID 28108736, 2017). "Knockdown of SNHG20 could suppress cell proliferation, increase cell apoptosis, and impair stemness properties, therefore preventing cancer progression." (PMID 34345203, 2021). "lncRNA small nucleolar RNA host gene 20 (SNHG20) was verified to be an oncogene in several cancers." (PMID 34345203, 2021). "Besides, accumulating evidence reveals that SNHG20 overexpression is also connected with poor clinical outcomes among cancer patients." (PMID 32675944, 2020). "It has been widely reported that the expression levels of SNHG20 are elevated in diverse types of cancers, indicating that SNHG20 may participate in cancer initiation and development." (PMID 32675944, 2020).
cancer (continued). "Moreover, up-regulated SNHG20 expression is capable of serving as an innovative predictive factor of inferior clinical outcomes in cancer patients." (PMID 32675944, 2020). "Up-regulated SNHG20 expression is ubiquitous in different kinds of cancers." (PMID 32675944, 2020). "Recently, the prognostic value of SNHG20 has been suggested in a series of cancers." (PMID 30846486, 2019). "Meanwhile, SNHG20 was overexpressed in cancer stem‐like cells." (PMID 30394668, 2019). "Notably, MEG3, MIAT, Malat1, SNHG20, SNHG12, Ftx, Pvt1, Mir9-3hg expression in cancer immune cells was associated with an immunosuppressive phenotype, while H19, SNHG6, Trp53cor1, MiR17hg and MiR142hg were linked to a pro-inflammatory phenotype in cancer." (PMID 40527978, 2025). "It worth noting that for LIHC, combinations of prognostic values of SNHG20 lncRNA and BUB1 mRNA, and also SNHG12 lncRNA and TMEM164 mRNA (associated with reduced OS with worse prognosis), could strengthen the predictive value of these markers for this cancer." (PMID 35140741, 2021). "In aggregate, the present meta-analysis elucidated that elevated SNHG20 expression is frequent in plenty of various types of cancers and qualified as a dependable and novel predictive factor of poor prognosis and clinicopathological features in cancer patients." (PMID 32675944, 2020). "However, the investigation of small nucleolar RNA host gene 20 (SNHG20) on cancer progression remains unknown." (PMID 27543107, 2016). "Our present work has demonstrated that SNHG20 expression is significantly upregulated in CRC tissues, suggesting that SNHG20 may be an adverse prognostic marker for CRC patients and a higher risk for cancer development." (PMID 27543107, 2016). "We also investigated commonly shared lncRNAs between COAD and READ (CRCs) and found the presence of MAGI2-AS3, GAS5, SNHG1, KCNQ1OT1, SNHG20, and MIR17HG in both cancers." (PMID 35140741, 2021). "The invasion and migration of cancer cells have close relationship with EMT process, thus the effect of SNHG20 and miR-148a on the expression of EMT-related proteins was measured." (PMID 34836544, 2021). "This lncRNA is also involved in vasculogenic mimicry, a process of pseudo-vascular formation in highly aggressive cancers, via enhancement of ZRANB2/SNHG20/FOX1 axis." (PMID 32318335, 2020). "In addition, we found that the knockdown of lncRNA SNHG20 can sharply inhibit the growth and metastasis of SCC25 and CAL27 cells, which indicates that lncRNA SNHG20 plays a role in promoting cancer during the progression of OSCC." (PMID 34282711, 2021). "However, the clinical relevance of SNHG20 and its molecular mechanisms affecting cancer cell phenotype have not been documented." (PMID 28981099, 2017).
SNHG20 also shares sentences with these, for which no sentence is quoted: gastric tumor (2 papers); neuroblastoma (2); oral squamous cell carcinoma (2); cancers of the reproductive system (1); digestive system cancer (1); glioblastoma (1); head and neck neoplasm (1); nasopharyngeal carcinoma (1); rectal adenocarcinoma (1); respiratory system cancer (1); soft tissue sarcoma (1).